METTL3 (methyltransferase 3, N6-adenosine-methyltransferase complex catalytic subunit)
Diseases named in the same sentence as METTL3 in open-access papers (continued):
Sharing a sentence is not in itself a finding about the gene and the disease.
non-alcoholic steatohepatitis (4 papers, 2022 to 2025). "Hepal-6-Luc cells expressing control (sgNC) or METTL3 knockout (sgMETL3) were implanted into the nonalcoholic steatohepatitis (NASH) livers of C57BL/6 mice, followed by treatment with anti-CD8α or immunoglobulin (Ig) G control." (PMID 37586322, 2023). "Methyltransferase METTL3 in non‐alcoholic steatohepatitis (NASH) could induce the deacetylation of H3K27 and H3K9 by recruiting HDAC1/2 on the CCL2 promoter, thus inhibiting the expression of CCL2 and inhibiting the progression of NASH." (PMID 36872292, 2023). "Conversely, METTL3 knockdown increased the free fatty acid uptake mediated by CD36, and the inflammation reaction induced by C-C motif chemokine ligand 2 (CCL2), as the result, lead to the progression from NAFLD to non-alcoholic steatohepatitis (NASH)." (PMID 36157445, 2022).
pneumonia (4 papers, 2023 to 2025). An acute, acute and chronic, or chronic inflammation focally or diffusely affecting the lung parenchyma, caused by an infection in one or both of the lungs (by bacteria, viruses, fungi, or mycoplasma.). "This research seeks to elucidate the regulatory mechanism of METTL3 in lung injury in neonatal mice with Spn-induced pneumonia, establishing novel theoretical foundations for therapeutic strategies for pneumonia." (PMID 41105618, 2025). "Circ_0001239 overexpression or KLF10 knockdown reversed the protective effects of low expression of METTL3 on lung damage in neonatal mice with pneumonia." (PMID 41105618, 2025). "Next, we measured the circ_0001239 expression and found that the circ_0001239 expression was upregulated in the pulmonary tissue of neonatal mice with Spn-induced pneumonia but was downregulated in the pulmonary tissue with low expression of METTL3 (P < 0.01)." (PMID 41105618, 2025). "First, our investigation was limited to validating the downstream METTL3-mediated molecular mechanisms in a neonatal mouse model of Spn-induced pneumonia." (PMID 41105618, 2025). "First, our experiment demonstrates that METTL3 is upregulated in lung injury of neonatal mice with Spn-induced pneumonia, and reducing METTL3 expression alleviates pneumonia." (PMID 41105618, 2025). "In conclusion, these findings suggest that circ_0001239 overexpression attenuates the protective effects of METTL3 downregulation on Spn-induced pneumonia in neonatal mice." (PMID 41105618, 2025). "In this study, an SP‐induced pneumonia cell model was established, which revealed that METTL3 was highly expressed in AECs during pneumonia." (PMID 38757482, 2024). "The literature has indicated markedly increased METTL3 expression in pediatric pneumonia patients and cell models." (PMID 38757482, 2024). "METTL3 was expressed at high levels in both pediatric pneumonia patients and cellular models, where downregulation of METTL3 inhibited LPS-induced apoptosis." (PMID 39273267, 2024). "Our experiment aligns with this observation, demonstrating that circ_0001239/YTHDC2-mediated KLF10 upregulation alleviates Spn-induced lung injury, whereas KLF10 downregulation diminishes the protective effect of METTL3 knockdown in neonatal mice with Spn-induced pneumonia." (PMID 41105618, 2025). "However, the specific downstream pathway of METTL3 in Spn-triggered pneumonia remains to be elucidated." (PMID 41105618, 2025). "Therefore, the METTL3-mediated m6A modification in circ_0001239 suggests a potential therapeutic strategy for pneumonia treatment." (PMID 41105618, 2025). "Therefore, METTL3 downregulation reduces SP‐induced pneumonia by alleviating apoptosis and inflammatory injury of AECs." (PMID 38757482, 2024). "The role of METTL3 in lung injury of neonatal mice with Spn-induced pneumonia remains unclear." (PMID 41105618, 2025). "In conclusion, METTL3 aggravates Spn-induced lung injury via m6A-dependent circ_0001239/YTHDC2/KLF10 axis, thereby providing potential therapeutic targets for severe pneumonia." (PMID 41105618, 2025). "To summarize, our study unveils that METTL3 upregulates circ_0001239 expression via m6A modification, increases the binding of circ_0001239 to YTHDC2, and inhibits KLF10 expression, ultimately worsening lung injury in neonatal mice with Spn-induced pneumonia." (PMID 41105618, 2025). "Additionally, the upstream regulatory mechanisms of METTL3 and downstream regulatory mechanisms of KLF10 should be further investigated, which may lead to the identification of new therapeutic approaches for pneumonia intervention." (PMID 41105618, 2025). "Furthermore, it has been observed that METTL3 downregulation can reduce m6A modification on the enhancer of zeste homolog 2 (EZH2) mRNA, thereby decreasing EZH2 expression and inhibiting inflammation and cell apoptosis in a pneumonia cell model." (PMID 38757482, 2024).
sarcoma (4 papers, 2019 to 2025). A usually aggressive malignant neoplasm of the soft tissue or bone. "Based on an online analysis of TCGA database, we found that METTL3 was upregulated in sarcoma tissue samples (n = 260) compared to normal tissues (n = 2)." (PMID 40510136, 2025). "Moreover, METTL3 and m6A binding protein YTHDC1 are responsible for DSBs HR repair in human sarcoma U2OS cells; METTL3 depletion enhances the sensitivity to DNA-damaging therapy." (PMID 35279688, 2022).
abdominal aortic aneurysm (3 papers, 2022). Enlargement and ballooning of the vessel that supplies arterial blood to the abdomen, pelvis and legs. "The development and progression of abdominal aortic aneurysm has been suggested to be induced through METTL3-mediated maturation of miR-34a and decreased Sirtuin 1 (Sirt1) mRNA expression." (PMID 35991314, 2022). "Accordingly, knockdown of METTL3 protects from development of abdominal aortic aneurysm, and this therapeutic effect is inhibitable by either miR-34a silencing or SIRT1 overexpression." (PMID 35991314, 2022). "Interestingly, the levels of METTL3 in smooth muscle cells of the aortic were also significantly upregulated in Ang-II-induced mouse abdominal aortic aneurysm model." (PMID 35836108, 2022). "Although a published study has reported that m6A levels are higher in the aortic tissues of abdominal aortic aneurysm (AAA) patients than in healthy aortic tissues 20, the expression pattern and role of METTL3 in AD are unclear." (PMID 35844806, 2022). "Furthermore, METTL3 has been shown to promote Ang II- and CaCl2-induced abdominal aortic aneurysm by accelerating primary microRNA-34a maturation and inhibiting SIRT1 expression 33, and METTL3 also exacerbates oscillatory stress-induced atherogenesis." (PMID 35844806, 2022).
acute lung injury (3 papers, 2024 to 2025). A condition of lung damage that is characterized by bilateral pulmonary infiltrates (pulmonary edema) rich in neutrophils, and in the absence of clinical heart failure. "Additionally, neutrophil extracellular traps (NETs) have been shown to facilitate the transcription of METTL3-driven mitochondrial reprogramming, which amplifies ferroptosis during secondary acute lung injury." (PMID 41142801, 2025). "Inhibition of METTL3 may potentially exhibit anti-apoptotic and protective effects against acute lung injury (ALI) by restoring the expression of neprilysin." (PMID 39010105, 2024).
cervical tumor (3 papers, 2022 to 2025). "Research indicates that m6A regulators like METTL3, METTL14, and YTHDF1 are overexpressed in cervical tumors compared to normal tissues, with elevated METTL3 and YTHDF1 levels linked to poorer prognosis." (PMID 41029427, 2025). "Expression levels of methyltransferase-like 3 (METTL3) are increased in cervical tumor tissues." (PMID 36976668, 2023).
cognitive decline (3 papers, 2023 to 2025). "METTL3 deficiency enhances the infiltration of monocyte-derived macrophages into the AD brain and Aβ clearance, subsequently improving the cognitive decline." (PMID 36881554, 2023). "Our study supports a link between excessive m6A and tau pathology and shows that inhibiting the m6A writer METTL3 with small molecule STM2457 reduces tau deposition, mitigates neurodegeneration, and prevents cognitive decline in PS19 mice." (PMID 41510223, 2025). "For example, altered METTL3 or YTHDF2 activity in excitatory neurons has been shown to impair long-term potentiation and accelerate cognitive decline, while increased FTO-mediated demethylation in microglia promotes pro-inflammatory cytokine production and blood-brain barrier disruption." (PMID 40624693, 2025).
Down syndrome (3 papers, 2021 to 2024). "In contrast, Down syndrome features abnormal METTL3 expression, which post-transcriptionally enhances SH3BGR mRNA." (PMID 39237501, 2024). "In the present study, we observed a decrease in both m6A modification and the m6A methyltransferase METTL3 in fetal hearts of Down syndrome." (PMID 39237501, 2024). "To elucidate the pathogenetic mechanisms underlying this condition, we explored the role of RNA m6A methylation, regulated by METTL3, in DS cardiac development and its impact on the expression of SH3BGR, a gene located at Down syndrome congenital heart disease (DS-CHD) minimal region." (PMID 39237501, 2024).
endothelial dysfunction (3 papers, 2022 to 2025). In vascular diseases, endothelial dysfunction is a systemic pathological state of the endothelium (the inner lining of blood vessels) and can be broadly defined as an imbalance between vasodilating and vasoconstricting substances produced by (or acting on) the endothelium. "Collectively, these results underline that METTL3 plays an important role in preventing EndMT and endothelial dysfunction in hPAECs." (PMID 38741032, 2024). "Next, to clarify whether METTL3 deficiency induces endothelial dysfunction, we crossed tamoxifen-inducible endothelial-specific Mettl3-deficient (EC-Mettl3KO) mice." (PMID 35001873, 2022). "Oscillatory shear stress downregulates the methyltransferase METTL3, destabilizing EGFR mRNA and thereby exacerbating endothelial dysfunction." (PMID 41462662, 2025). "Our data revealed that downregulation of METTL3 and hypomethylation mediate OS-induced endothelial dysfunction and atherogenesis both in vivo and in vitro, indicating that the THBS1/EGFR axis is a key regulatory target of METTL3-dependent EC activation." (PMID 35001873, 2022). "Adenovirus-mediated METTL3 overexpression significantly reduced EGFR activation and endothelial dysfunction in the presence of OS." (PMID 35001873, 2022).
endotoxemia (3 papers, 2023 to 2024). "In lipopolysaccharide (LPS)-induced endotoxemia, METTL3 controls neutrophil release from the bone marrow into the circulation in a TLR4-signaling-dependent mechanism involving surface expression of CXC chemokine receptor 2 (CXCR2)." (PMID 39686999, 2024). "In endotoxemia, METTL3-mediated m6A-modification of Tlr4 showed increased translation and slowed degradation, which was critical for neutrophil activation." (PMID 37486903, 2023). "Methyltransferase-like 3 (METTL3), one of the key m6A RNA methylation writers, could work as a potential therapeutic target for LPS-induced endotoxemia." (PMID 37701433, 2023).
fatty liver (3 papers, 2021 to 2025). "Thus, the loss of Mettl3 in the liver promotes hepatic steatosis mainly by increasing Cd36 expression." (PMID 34893641, 2021). "However, owing to the different etiology of fatty liver disease caused by different molecular mechanisms, Mettl3 may participate in the pathogenesis of fatty liver disease related to glucose metabolism disorders." (PMID 37335109, 2023). "To further determine the exact roles of Mettl3 in the progression of fatty liver disease, we crossed Mettl3flox/flox mice with heterozygous Alb-Cre mice to obtain Mettl3flox/wt; Alb-Cre mice." (PMID 37335109, 2023). "Among genes related to NAFLD, both m6A peaks and mRNA levels of Srebp1 (also named Srebf1) were significantly decreased, which further indicates that lipogenesis likely contributes little to fatty liver observed in Mettl3-HKO mice." (PMID 34893641, 2021). "m6A methyltransferases METTL3/METTL14 promote the expression of genes related to lipid synthesis (such as Srebp1 and Fasn), exacerbating hepatic steatosis." (PMID 40699703, 2025).
glomerulosclerosis (3 papers, 2022 to 2025). A hardening of the kidney glomerulus caused by scarring of the blood vessels. "Additionally, PAS and Masson's trichrome staining revealed that METTL3 deficiency significantly reduced STZ‐induced glomerular sclerosis and extracellular matrix accumulation, alongside a decrease in the albumin/creatinine ratio (UACR)." (PMID 40421968, 2025). "METTL3 knockout inhibited the abnormal activation of the MDM2‐Notch1 pathway, preventing podocyte death during the initial phases of glomerular injury and alleviating glomerulosclerosis." (PMID 40421968, 2025). "Targeting METTL3 may prevent MDM2-Notch1 mediated podocyte injury and glomerulosclerosis in DKD." (PMID 41009556, 2025).
IgA nephropathy (3 papers, 2024). "Furthermore, METTL3 protein expression was significantly increased in the tissues of CKD patients with diabetic or IgA nephropathy." (PMID 38297163, 2024).
keloid (3 papers, 2022 to 2025). An irregularly shaped, elevated mark on the skin caused by deposits of excessive amounts of collagen during wound healing. "Among all m6A regulators, the levels of METTL3 and WTAP were significantly higher in keloid samples, while the levels of ALKBH5, FTO, and METTL14 exhibited little differences." (PMID 40860194, 2025). "The Western blotting results showed that the proteins of METTL3 and WTAP in keloid were significantly higher than those in normal skin (p < 0.05)." (PMID 36263010, 2022). "They collected 14 pairs of normal skin and keloid tissues and found that WTAP and METTL3 protein expression was higher in keloid tissues than in normal tissues." (PMID 37122849, 2023).
lymphoma (3 papers, 2019 to 2024). A malignant (clonal) proliferation of B- lymphocytes or T- lymphocytes which involves the lymph nodes, bone marrow and/or extranodal sites. "In clinical lymphoma samples, the expression of METTL3, YTHDF1, and TLR9 was highly correlated with immune cells infiltration." (PMID 38537697, 2024). "This analysis suggests that METTL3, YTHDF1, and TLR9 may have influence on lymphoma development and prognosis, via modulating immune microenvironments." (PMID 38537697, 2024). "As METTL3 plays a significant role in normal hematopoiesis, an increasing number of studies on hematology malignancies have been reported in recent years, including AML, acute lymphocytic leukemia (ALL), CML, and lymphomas." (PMID 35574332, 2022).
metabolic syndrome (3 papers, 2020 to 2024). A cluster of metabolic risk factors for CARDIOVASCULAR DISEASES and TYPE 2 DIABETES MELLITUS. "Together, these results indicate that Mettl3 overexpression can aggravate liver metabolic disorders and hepatogenous diabetes, suggesting that high level of Mettl3 may be a risk factor for HFD-induced metabolic syndrome." (PMID 33160098, 2020). "Mechanistically, Mettl3 depletion-mediated m6A loss caused extended RNA half-lives of metabolism-related genes, which consequently protected mice against HFD-induced metabolic syndrome." (PMID 33160098, 2020). "It has also been shown that Mettl3-IGFBP2-mediated changes in m6A levels increase HDAC1 mRNA stability to affect FGF21 expression, leading to liver injury and insulin resistance caused by hepatic steatosis and ultimately the development of metabolic syndrome." (PMID 38562618, 2024). "Taken together, these results suggest that Mettl3 depletion in liver could protect mice against HFD-induced metabolic syndrome, indicating that Mettl3 might be a potential therapeutic target for liver metabolic diseases." (PMID 33160098, 2020). "Considering that overexpression of Mettl3 can aggravate liver metabolic disorders and hepatogenous diabetes induced by HFD, we supposed that Mettl3 ablation in liver could resist HFD-induced metabolic syndrome." (PMID 33160098, 2020). "Therefore, we hypothesized that METTL3/14 plays a joint role in pyroptosis death by regulating NLRP3, thus influencing metabolic syndrome development." (PMID 38562618, 2024).
osteomyelitis (3 papers, 2022 to 2025). An acute or chronic inflammation of the bone and its structures due to infection with pyogenic bacteria. "In conclusion, this study aims to investigate the roles of butyrate and METTL3 in the osteogenesis of osteomyelitis." (PMID 40889211, 2025). "Hu and Jiao enrolled 33 osteomyelitis patients and demonstrated up-regulated METTL3 expression in the bone marrow puncture tissue samples in comparison with samples from healthy control." (PMID 38665846, 2024). "In the m6A regulators-associated molecular subtypes, METTL3, CBLL1 and LRPPRC were significantly more highly expressed in subgroup A osteomyelitis than in subgroup B, while RBM15B and YTHDC1 expression were higher in subgroup A osteomyelitis." (PMID 36544487, 2022). "We speculate that the decrease in METTL3 expression by butyrate in osteomyelitis affects osteogenic activity by regulating the autophagy of osteoblasts." (PMID 40889211, 2025). "We speculate that exploring the relationship between butyrate, METTL3, and osteomyelitis is of great significance." (PMID 40889211, 2025). "METTL3 was also closely correlated to immune infiltration and immune response of osteomyelitis." (PMID 38665846, 2024). "In this study, we indicated that activated B cells had higher infiltration abundance in the group with high METTL3 expression, suggesting that METTL3 may play an important role in the immune response of B cells and be closely related to the immune regulation of osteomyelitis." (PMID 36544487, 2022). "Furthermore, METTL3 and LRPPRC were determined to be closely associated with immune infiltration by immune infiltration analysis, which will provide guidance for personalized immunotherapy of osteomyelitis patients in the future." (PMID 36544487, 2022). "Among the 6 m6A regulators, METTL3 and LRPPRC were highly expressed in subgroup A osteomyelitis, whereas YTHDC1 was highly expressed in gene cluster B osteomyelitis." (PMID 36544487, 2022). "We found that METTL3 was highly expressed and YTHDF2 was expressed at low levels in osteomyelitis samples and validated this finding in a rat model of osteomyelitis." (PMID 36544487, 2022). "Among them, two m6A regulators (METTL3 and LRPPRC) were closely related to immune infiltration in patients with osteomyelitis." (PMID 36544487, 2022). "Visualization of the results by boxplot and heatmap suggested that the 5 regulators were differentially expressed between the two m6A subtypes, with METTL3, CBLL1 and LRPPRC highly expressed in cluster A osteomyelitis, RBM15B and YTHDC1 highly expressed in cluster B osteomyelitis." (PMID 36544487, 2022). "The qRT‒PCR results showed that the mRNA expression of METTL3, YTHDC1, RBM15B, LRPPRC and CBLL1 in osteomyelitis tissues was significantly increased, while that of YTHDF2 was significantly decreased (p < 0.05), which was consistent with the results of bioinformatics analysis." (PMID 36544487, 2022). "It is suggested that METTL3 and YTHDF2 may be involved in promoting osteogenic differentiation and attenuating the inflammatory response in the inflammatory environment of osteomyelitis, making them potential therapeutic targets." (PMID 36544487, 2022). "Based on the 6 significant m6A regulators with differential expression in the dataset, we further validated the expression of the 6 m6A regulators (METTL3, YTHDC1, YTHDF2, RBM15B, LRPPRC and CBLL1) in 10 osteomyelitis samples and 10 control samples by qRT‒PCR analysis." (PMID 36544487, 2022).
ovarian tumor (3 papers, 2021 to 2023). "METTL3 stimulates AXL mRNA translation and epithelial–mesenchymal transition, thereby promoting growth and invasion of ovarian tumors." (PMID 34363020, 2021).